KDM5D (lysine demethylase 5D)
Diseases named in the same sentence as KDM5D in open-access papers (continued):
Sharing a sentence is not in itself a finding about the gene and the disease.
bladder tumors (1 paper, 2024). "The critical role of KDM5D in tumor immunity is validated by another research, which reveals that KDM5D and ubiquitously transcribed tetratricopeptide repeat containing, Y-linked (UTY) are responsible for the enhanced immune escape of bladder tumors with LOY (loss of Y chromosome)." (PMID 39872442, 2024).
Constipation (1 paper, 2024). Infrequent or difficult evacuation of feces. "The present results suggest that C3 deficiency-induced constipation may be associated with 1237 upregulated genes including PNLIP, CEL, CPB1, CTRL, PNLIPRP1, and REG1 as well as 1292 downregulated genes including Eif2s3y, UTY, KDM5D, IGKV6-32, Olfr870, and DDX3Y." (PMID 39273477, 2024).
glaucoma (1 paper, 2023). Increased pressure in the eyeball due to obstruction of the outflow of aqueous humor. "Database analysis revealed that seven host genes (NEAT1, SAMD12, KDM5D, ZFY, EIF1AY, TXLNGY, and DDX3Y) of nine DEcircRNAs were also differentially expressed in blood samples of patients with glaucoma, and the trend of differential expression of circRNAs and host genes was consistent." (PMID 37805546, 2023).
glioma (1 paper, 2025). A benign or malignant brain and spinal cord tumor that arises from glial cells (astrocytes, oligodendrocytes, ependymal cells). "These single-cell studies were confirmed by qPCR-RT, showing a high expression level of the Y-chromosome genes, namely Eif2s3y, Kdm5d, and Uty, in rat glioma 101.8 samples in male but not in female recipients." (PMID 41009560, 2025).
head and neck cancer (1 paper, 2023). A primary or metastatic malignant neoplasm affecting the head and neck. "Our study suggests that KDM5D regulates persister head and neck cancer cells by modulating AURKB expression." (PMID 36982384, 2023).
Hepatic steatosis (1 paper, 2017). Steatosis is a term used to denote lipid accumulation within hepatocytes. "It was suggested that lnc-KDM5D-4 was then implicated in hepatic steatosis which can occur independently of insulin resistance in the liver." (PMID 29196750, 2017).
hepatocellular carcinoma (1 paper, 2017). A malignant tumor that arises from hepatocytes. "This study provides the first evidence of the expression of Y-linked lincRNA transcripts such as lnc-KDM5D-4:1, lnc-ZFY-1:1, lnc-ZFY-2:1, lnc-RBMY1B-1:1, lnc-RBMY1B-1:4, lnc-USP9Y-1:4, and lnc-HSFY2-3:6 in human hepatocellular carcinoma (HCC)." (PMID 29196750, 2017).
lung adenocarcinoma (1 paper, 2016). A carcinoma that arises from the lung and is characterized by the presence of malignant glandular epithelial cells. "At most, the gene expression of a histone demethylase, KDM5D, and a histone deacetylase, HDAC11, was considerably decreased among 18 and 4 lung adenocarcinoma cell lines, respectively." (PMID 27042856, 2016).
meningioma (1 paper, 2013). A generally slow growing tumor attached to the dura mater. "The expression pattern of JARID1D/KDM5D/SMCY significantly differed in meningiomas of male and female patients and contributes to the female predominance of this tumor." (PMID 23922798, 2013).
renal carcinoma (1 paper, 2017). A carcinoma arising from the epithelium of the renal parenchyma or the renal pelvis. "However, further detailed analysis through future functional studies is warranted to understand the exact function and pathway context of KDM5D in renal cancer." (PMID 28332632, 2017).
thyroid (1 paper, 2024). "To clarify the role of KDMs in thyroid tumorigenesis, we next examined the mRNA expressions of KDM5C, KDM5D, and KDM6A by RT-PCR in a set of normal thyroid and tumor tissue samples from 77 patients, who underwent surgery for thyroid nodules." (PMID 38610938, 2024).
tumor (44 papers, 2008 to 2026). "This genetic relationship between KDM5C and KDM5D mutation is consistent with the human data that indicates that KDM5C mutant male ccRCC tumours display concomitant loss of KDM5D function through Y chromosome loss." (PMID 39955388, 2025). "Mutation of KDM5D in male 786-O cells prevented xenograft tumour formation and this phenotype was unexpectedly rescued by co-mutation of KDM5C, consistent with the co-occurrence of KDM5C mutation and loss of the Y chromosome in ccRCC." (PMID 39955388, 2025). "Further consistent with this idea, the up- and down-regulation of these genes were reversed by the co-mutation of KDM5C, which restores tumour formation by KDM5D mutant cells." (PMID 39955388, 2025). "Histologically, we focused on cellular findings correlated with worse clinical outcomes in SCC, including nuclear size and tumor budding, and stromal findings to clarify clinicopathological characteristics of patients with KDM5D copy number loss." (PMID 37974379, 2024). "Currently, the molecular mechanism underlying the paucity of tumor T‐cell infiltration within tumors and subsequent downregulation of genes associated with the immune response in SCCs with copy number loss of KDM5D is unclear." (PMID 37974379, 2024). "Loss of nuclear KDM5D was associated with increased KDM5D expression in the cytoplasm of tumor cells." (PMID 38610938, 2024). "Deletion of Kdm5d sensitized cancer cells to CD8+ T cell‐mediated killing, while Kdm5d overexpression diminished CD8+ T cell infiltration at the tumor invasive front, mimicking the effect of KRAS mutation." (PMID 37679889, 2023). "Following exposure to ATRi, KDM5D-deficient PC cells show curtailed proliferation and increased apoptosis indicative of a tumour-targeted synthetic lethal interaction." (PMID 34127738, 2021). "This was also observed at the transcriptional level where KDM5D mutation increased the expression levels of a series of putative tumour suppressor genes and decreased the expression of putative pro-proliferative genes, while KDM5C co-mutation reversed these transcriptional changes." (PMID 39955388, 2025). "By inference from 786-O cells, loss of the Y chromosome and KDM5D function may represent a barrier to further tumour evolution, which can be alleviated by KDM5C mutation, or vice versa." (PMID 39955388, 2025). "Though the role of the loss of certain ChrY genes has been partially characterized in BCs (e.g., KDM5D loss conferring an aggressive tumor phenotype with high responsiveness to immunotherapy) the exact dynamics by which LOY contributes to a tumor’s phenotype is less clear." (PMID 41214505, 2025). "Furthermore, LOY genes KDM6C and KDM5D correlates with adverse prognosis in bladder cancer patients, further compromising anti-tumor immunity within LOY-associated tumors." (PMID 39731171, 2024). "Additionally, the precise identification of the molecular pathways linking the loss of UTY and/or KDM5D to CD8+ T cell fatigue within the tumor microenvironment is crucial for advancing our understanding and developing targeted therapeutic strategies." (PMID 39594721, 2024). "KDM5D, encoded on the Y chromosome, has recently been shown to be a tumor suppressor gene." (PMID 35805040, 2022). "For KDM5D encoded on the X-chromosome, a direct interaction with the androgen receptor in the tumor cell nucleus could be demonstrated, and a reduction in the expression of KDM5D leads to disruption of the androgen receptor pathway." (PMID 32629877, 2020). "Deletion of Kdm5d improved tumor outcomes in mouse models, in part through indirect effects on the CD8+ T cell compartment." (PMID 41580387, 2026). "Y chromosome genes Kdm5d and Uty were found to be crucial to tumor growth, as single knockouts of each in cancer cells significantly increased tumor growth while overexpression diminished tumor size." (PMID 41580387, 2026).
tumor (continued). "By the 2020s several ChrY genes which potentially suppress tumor growth and aggression as well as modify PC chemotherapy sensitivity have been identified, the most notable of which is lysine demethylase 5D (KDM5D)." (PMID 41214505, 2025). "Regarding the tumor-suppressive genes of the ChrY associated with cancer initiation events, TMSB4Y and KDM5D are the most noteworthy but the UTY gene possesses some tumor suppressive activity as well and is worth mentioning." (PMID 41214505, 2025). "Several studies have reported the male-specific histone lysine demethylase 5D (KDM5D) gene as a tumor suppressor in PCa." (PMID 39594721, 2024). "In metastatic prostate cancer, frequent deletion of the KDM5D gene predicts poor prognosis, limiting tumor invasiveness through H3K4 demethylation and suppression of matrix metalloproteinase expression." (PMID 39731171, 2024). "Further findings indicate that KDM5D is a tumor suppressor inhibiting the division, invasion, and EMT of cancer cells." (PMID 38769556, 2024). "Tumor formation experiments in nude mice showed that the low expression group of KDM5D showed increased growth ability of CRC cells in nude mice, resulting in more volume, increased tumor weight and Ki-67 index." (PMID 38326863, 2024). "KDM5D expression was upregulated in HNSCC tumor cells, cancer stem cells, and cisplatin-resistant cells with biologically distinct signaling alterations." (PMID 36982384, 2023). "Tumor specimens from the HNSCC cohort revealed a significantly higher expression level of KDM5D protein than normal adjacent tissues." (PMID 36982384, 2023). "There is growing evidence that EMT is necessary for tumor metastasis, and KDM5D gene knockout increases the expression of key EMT regulators (such as N-cadherin and Slug)." (PMID 35493099, 2022). "The knockdown of two different isoforms of KDM5D using the short interfering RNA (siRNA) approach confirmed its tumor suppressor role in a PC cell line." (PMID 34983649, 2022). "Analysis of sequencing read coverage of 20 MSY genes and RNA-seq data obtained from normal and tumor tissues also showed that the expression of epigenetic modifiers KDM5D and/or KDM6C is reduced due to LOY in clear cell renal cell carcinoma (ccRCC)." (PMID 34983649, 2022). "Tumour KDM5D abundance, as gauged through RNA-seq, was available through the Kaplan–Meier plotter platform across 14 non-sex-specific cancer types totalling 2423 male patients." (PMID 34127738, 2021). "This suggests that SCC with KDM5D copy number may be characterized by its unique tumor microenvironment (TME)." (PMID 37974379, 2024). "Our multiplex immunohistochemical results along with transcriptome data indicate that SCCs with copy number loss of KDM5D can be ‘cold tumors’, which are characterized by the paucity of tumor T‐cell infiltration and usually do not respond to immunotherapy." (PMID 37974379, 2024). "Notably, recent research has notably highlighted the upregulation of the Y chromosome gene KDM5D in KRAS-mutated CRC, which influences tumor cell adhesion and immune responses through the KRAS-STAT4 signaling pathway." (PMID 39731171, 2024). "KDM5D knockdown significantly reduced tumor sphere formation in both PT-SAS and PT-FaDu cells." (PMID 36982384, 2023). "Moreover, the clinicopathological data suggest that KDM5D contributes to the emergence of specific tumor cell subsets after chemotherapy, namely platinum-tolerant persister HNSCC cells." (PMID 36982384, 2023). "For example, the interaction between ZMYND8 and PKCβ or TROJAN may induce pro-oncogenic effects, while interaction between ZMYND8 and KDM5C, KDM5D, or ZNF592 may cause tumor-suppressive effects." (PMID 33670804, 2021). "Our observation that tumour deficiency of KDM5D has significant negative implications for survival is consistent with the wider deleterious effects of mosaic LOY in peripheral blood." (PMID 34127738, 2021).
tumor (continued). "Moreover, looking beyond the role of KDM5D as an epigenetic modifier, evidence accumulated from various tumour classes also points to a redistribution, or perturbation of DNA methylation upon copy number alteration." (PMID 34127738, 2021). "The KDM5 subfamily (also known as JARID1 subfamily) consists of four members, KDM5A (JARID1A), KDM5B (JARID1B), KDM5C (JARID1C) and KDM5D (JARID1D) whose deregulation in various kinds of cancer has been widely documented to contribute significantly to tumor initiation and progression." (PMID 31060229, 2019). "In addition to analyses of human ccRCC tumours segregated based on Y chromosome and KDM5C mutation status, functional experiments introducing Kdm5c and Kdm5d mutations into mouse autochthonous ccRCC models could be informative." (PMID 39955388, 2025). "KDM5A and KDM5B have been indicated to be carcinogenic in numerous studies, while KDM5C and KDM5D may function as tumor suppressors, although the evidence is conflicting which may be due to the specific tumor microenvironment and different experimental conditions." (PMID 38769556, 2024). "The results showed that ZNF439 and KDM5D were highly expressed in normal tissues, whereas KMO, FT57, HDAC9, GSAP, and CCR7 were highly expressed in tumor tissues." (PMID 40145017, 2025). "Analysis of the expression of the TILB-related signature genes in B Plasma cells showed that KMO, IFT57, HDAC9, GSAP, and CCR7 were significantly highly expressed in tumor tissue, while ZNF439 and KDM5D showed a similar trend." (PMID 40145017, 2025). "Deletion of KDM5D conversely enhances tumor cell adhesion and improves CD8 + T cell-mediated tumor surveillance, enhancing immune response effectiveness." (PMID 39731171, 2024). "KRAS–STAT4 pathway targets a Y chromosome gene KDM5D, which inhibits the expression of tight junction proteins angiomotin (AMOT) and MHC-I through epigenetic regulation, ultimately driving tumor metastasis and immune escape in a male-specific manner." (PMID 39872442, 2024). "Strikingly however, KDM5D mutant cells failed to form xenograft tumours but the combination of KDM5C and KDM5D mutations restored the ability to form tumours." (PMID 39955388, 2025). "The expression of EIF1AY and KDM5D was elevated in tumour samples but almost absent in normal pituitary tissue." (PMID 39548559, 2024). "However, KDM5D, or JARID1D/SMCY, has been reported to have a tumor suppressive function in prostate cancer." (PMID 37880235, 2023). "In addition, patients with KDM5D-overexpressing HNSCC had more advanced disease, lower survival, and a higher likelihood of tumor recurrence following platinum therapy." (PMID 36982384, 2023). "We then quantified to what extent the negative expression correlation between KDM5D and MYBL2 observed in vitro was reflected as an inverse association of KDM5D and MYBL2 in tumor tissue from patients." (PMID 36087093, 2022).
cancer (43 papers, 2008 to 2026). A tumor composed of atypical neoplastic, often pleomorphic cells that invade other tissues. "This work illustrates, in a manner supported by patient derived data, a context in which KDM5D activity is responsible for the prevention of cancer escalation and the loss thereof, the development of metastatic disease." (PMID 41214505, 2025). "In this context, KDM5D loss contributes to the progression of a cancer to the stage of metastasis indirectly due to normally occupying a role in which it represses the activation of a factor directly responsible for this process." (PMID 41214505, 2025). "The finding that elevation of MYBL2 had a more consistent association with poorer mHSPC outcomes than lower KDM5D is consistent with MYBL2 being a transcription factor controlled by other factors that promote many of the hallmarks of cancer." (PMID 36087093, 2022). "CD8+ T cells exposed to Kdm5d deficient cancer cells showed more efficient killing." (PMID 41580387, 2026). "Loss of KDM5D has been implicated in chemoresistance in cancer; however, its role in CHK1i sensitivity is unknown." (PMID 41308413, 2025). "Moreover, activated ATR signaling with the loss of KDM5D expression can be exploited to elicit synthetic lethality of ATR inhibition in cancer cells." (PMID 37974379, 2024). "For example, the X-linked lysine demethylases 6A and 5C, as well as the Y-linked paralogs lysine demethylase 5D, may be regulators of the incidence and prognosis of sex-specific cancer." (PMID 38610938, 2024). "Finally, the fourth gene, KDM5D, encodes a lysine-specific demethylase whose activity suppresses the invasiveness of some cancers." (PMID 27058445, 2016). "To investigate whether transcriptional changes might underlie the different effects of KDM5C and KDM5D mutation on cancer cell behaviours, we conducted RNA-seq of triplicate samples of all 8 mutant 786-O cell populations and identified up- and down-regulated genes compared to sgCtrl cells." (PMID 39955388, 2025). "Further, the Y-encoded protein, KDM5D, interacts with the Sin3–HDAC complex, contributing to male-biased cancer progression." (PMID 41024254, 2025). "KDM5D, together with KDM5A, KDM5B, and KDM5C, belongs to the KDM5 family and has been implicated in various cancers and in the regulation of oncogenes and tumor suppressor genes." (PMID 41308413, 2025). "Specifically relating to PCs, KDM5D has been found to be severely downregulated in cancers with castration resistance and shortened survival time." (PMID 41214505, 2025). "Reduced expression of KDM5D in human cancer cells has been reported in various organs such as the prostate, kidney, stomach, and lung." (PMID 37974379, 2024). "In cancers, nuclear KDM5D was detected in 1/6 (16.6%) of FTCs, 2/6 (33.3%) of PTCs, and 0/2 (0%) of PDTCs." (PMID 38610938, 2024). "Kdm5d deletion in iKAP cancer cells decreased metastasis, while iAP male and female mice with enforced Kdm5d transgene expression showed more advanced cancer stages and increased metastasis rate." (PMID 37679889, 2023). "We determined the putative association of KDM5D expression with DTPC development and cancer stemness." (PMID 36982384, 2023). "The downregulation of ALDH1A3 in response to KDM5D silencing also suggested the role of the KDM5D/AURKB axis in modulating ALDH1A3-mediated cancer stemness, platinum tolerance, and transition towards the quiescent state of HNSCC cells." (PMID 36982384, 2023). "Nonetheless, further studies are required to confirm the specificity of Rh(III) complex 1 on KDM5A over KDM5B, KDM5C, KDM5D, or other lysine demethylases in other cancers to fully assess their potential in cancer treatment." (PMID 36509829, 2022). "Our in vitro data shows that over expression of KDM5D in cancer cells that are affected by LOY reduces cell viability." (PMID 28332632, 2017). "Furthermore, constitutive expression of Kdm5d in cancer cells resulted in decreased CD8+ T cell infiltration." (PMID 41580387, 2026).